RNA5-8SP2 (RNA, 5.8S ribosomal pseudogene 2)
Synonyms: RN5-8S2
Gene: Ribosomal RNA pseudogene on chromosome 16 (34,162,959 to 34,163,110, forward strand). Ensembl gene ENSG00000200434.
Diseases named in the same sentence as RNA5-8SP2 in open-access papers:
RNA5-8SP2 is named in the same sentence as 3 diseases in open-access papers, as found by Europe PMC text mining. Sharing a sentence is not in itself a finding about the gene and the disease.
RNA5-8SP2 shares sentences with these, for which no sentence is quoted: leukemia (1 paper); lung carcinoma (1); tumor (1).